HS6ST3 (heparan sulfate 6-O-sulfotransferase 3)
Description:
6-O-sulfation enzyme which catalyzes the transfer of sulfate from 3'-phosphoadenosine 5'-phosphosulfate (PAPS) to position 6 of the N-sulfoglucosamine residue (GlcNS) of heparan sulfate.
Synonyms: HS6ST-3
Tractability: Antibody: UniProt predicts a signal peptide or a membrane-spanning region; the Human Protein Atlas places it where antibodies can reach.
Gene: Protein-coding gene on chromosome 13 (96,090,107 to 96,839,562, forward strand). Ensembl gene ENSG00000185352.
Subcellular location: Membrane
Subcellular location (Human Protein Atlas): Nuclear membrane; Nucleoplasm; Actin filaments; Plasma membrane
Pathways (Reactome):
Metabolism: HS-GAG biosynthesis
Gene Ontology:
Molecular function: heparan sulfate 6-sulfotransferase activity; sulfotransferase activity
Biological process: heparan sulfate proteoglycan biosynthetic process
Cellular component: Golgi apparatus; membrane
Genetic constraint (gnomAD): Loss-of-function variants: 12 observed, 30.33 expected, observed/expected ratio (o/e) 0.4, 90% interval 0.25 to 0.64. The upper end of that interval is the gene's LOEUF score, 0.64, which puts it in group 2 of 6, group 1 being the genes least tolerant of losing a copy. Missense variants: 584 observed, 599.02 expected, observed/expected ratio (o/e) 0.97, 90% interval 0.91 to 1.04. Synonymous variants: 240 observed, 236.96 expected, observed/expected ratio (o/e) 1.01, 90% interval 0.91 to 1.13.
Homologues: Orthologues: chimpanzee HS6ST3 (99% identical), macaque HS6ST3 (98% identical), mouse Hs6st3 (95% identical), rat Hs6st3 (95% identical), pig HS6ST3 (94% identical), zebrafish hs6st3b (63% identical), zebrafish hs6st3a (56% identical), tropical clawed frog hs6st3 (43% identical), Drosophila melanogaster Hs6st (37% identical), Caenorhabditis elegans hst-6 (32% identical). Paralogues in human: HS6ST2 (56% identical), HS6ST1 (53% identical).
Diseases named in the same sentence as HS6ST3 in open-access papers:
HS6ST3 is named in the same sentence as 11 diseases in open-access papers, as found by Europe PMC text mining. Sharing a sentence is not in itself a finding about the gene and the disease. The quoted sentences say what the papers report.
breast carcinoma (1 paper, 2019). "HS6ST3 could promote breast cancer cell proliferation by upregulating IGF1R expression." (PMID 31921621, 2019).
diabetic retinopathy (1 paper, 2020). "Similarly, several genes implicated in diabetic retinopathy – classically considered a retinal vasculopathy– were differentially expressed by RGCs (e.g AKR1B1, HS6ST3 and MPRIP), suggesting that a primary neuropathic process may also be involved." (PMID 32555229, 2020).
dystrophinopathy (1 paper, 2022). "Among these genes, Pde4b is reported to affect the severity of dystrophinopathy, and Kcnma1, and Hs6st3 play roles in myogenesis." (PMID 36123393, 2022).
tumor (3 papers, 2007 to 2018). "Four somatic variations (RP1L1, PRB1, HS6ST3 and DCTN1) were simultaneously occurred in both primary tumor and PM cancer." (PMID 26330360, 2015).
HS6ST3 also shares sentences with these, for which no sentence is quoted: cancer (2 papers); chronic gastritis (1); gastric cancer (1); ischemic heart disease (1); lung carcinoma (1); metastatic cancer (1); Obesity (1).